SPP1 (secreted phosphoprotein 1)
Diseases named in the same sentence as SPP1 in open-access papers (continued):
Sharing a sentence is not in itself a finding about the gene and the disease.
liver cancer (continued). "Our previous work revealed that SPP1 was a leading pro-metastasis gene in HCC, but how HCC-derived SPP1 modified the PMN in target organs, especially in lungs, to fuel the metastasis of liver cancer remains to be further investigated." (PMID 39529085, 2024). "Thus, it can be seen that COMP, SPP1, and COL4A2 play important roles in the development of liver cancer." (PMID 38374893, 2024). "Additionally, models consisting of SPP1 and lecithin-cholesterol acyltransferase (LCAT) are good at predicting liver cancer diagnosis, prognosis and recurrence." (PMID 38374893, 2024). "Additionally, high‐dose BBR regulated the interactions from liver cancer immune cells to CD8+ T cells via ligand‐receptor pairs such as CCL3–CCR5, CCL5–CCR5, CXCL6–CXCR6, and SPP1–(ITGA4+ITGB1)." (PMID 39135526, 2024). "We hypothesized that the expression levels of SPP1 and CSF1 were related to the prognosis of liver cancer patients." (PMID 37097499, 2023). "However, in liver cancer tissue, ESR1 and FOBS genes were low in expression, while SPP1 genes were high in expression." (PMID 34238253, 2021). "Finally, single-gene GSEA analysis was performed on the three prognostic genes, ESR1, SPP1 and FOSB, that affect the survival time of liver cancer patients in order to explore the mechanism affecting the prognosis of liver cancer patients." (PMID 34238253, 2021). "Additionally, we investigated whether the core genes of HCCEvoSig were included in the CancerLivER database, which comprises over 594 liver cancer biomarkers, and found that four of 11 genes (ADH4, CYP2C9, SPP1 and SERPINE1) were included in the database." (PMID 40901047, 2025). "Therefore, to further investigate the relationship between SPP1 and immune infiltration, computational methods such as TIMER, XCELL, CIBERSORT, CIBERSORTABS, QUANTISEQ, MCP-COUNTER and EPIC were utilized to comprehensively evaluate SPP1 and the immune microenvironment of liver cancer." (PMID 39635536, 2024). "The results showed that UBE2C, PTTG1, TOP2A and SPP1 were positive, FCN3, SLC22A1, ADH4, CYP2C8, SLC10A1, and FBP1 were negative in liver cancer tissues." (PMID 38664521, 2024).
lung adenocarcinoma (70 papers, 2010 to 2026). A carcinoma that arises from the lung and is characterized by the presence of malignant glandular epithelial cells. "This is remarkable as the abundance of SPP1+ TAMs is associated with poor prognosis in lung adenocarcinoma and cervical cancer patients as well as the promotion of cancer stemness in pancreatic cancer." (PMID 39548496, 2024). "It has been found that lung adenocarcinoma exhibits high expression of SPP1 and that this has been associated with poor prognosis, while low expression of PECAM1 and PIK3R1 is associated with poor prognosis (P < 0.05)." (PMID 36688087, 2023). "The methylation level of SPP1 is significantly decreased in lung adenocarcinoma, and SPP1 is clearly associated with clinical lymph node metastasis." (PMID 36688087, 2023). "In the validation set, VEGFA, TIMP1 and SPP1 were still found to be significantly associated with the survival of lung adenocarcinoma patients." (PMID 37189418, 2023). "And in pancreatic adenocarcinoma, SPP1 expression levels were associated with patient prognosis and immune regulation, and in lung adenocarcinoma, SPP1 was found to be associated with drug resistance." (PMID 37259059, 2023). "Next, a survival analysis of the validated ligands revealed that the high expression ligand signals VEGFA, TIMP1, and SPP1 were significantly associated with a lower chance of survival in patients with lung adenocarcinoma." (PMID 37189418, 2023). "SPP1 is highly expressed in lung adenocarcinoma compared with normal lung tissue, and the high expression of SPP1 is associated with poor prognosis, while the high expression of PECAM1 and PIK3R1 is associated with good prognosis." (PMID 36688087, 2023). "SPP1 on TAMs was associated with a poor clinical course in lung adenocarcinoma patients, and the protumor function of SPP1 is potentially related to the chemoresistance and re-growth of cancer cells." (PMID 36139536, 2022). "With this in mind, the glycoprotein SPP1, which we identified as positively associated with SqCC risk, is produced by tumor-associated macrophages in vitro and induces PD-L1 expression in lung adenocarcinoma." (PMID 36404344, 2022). "SPP1 has been reported as an independent risk biomarker prognostic evaluation of patients with lung adenocarcinoma." (PMID 33072067, 2020). "(n=89), and multiplexed immunohistochemistry (IHC) staining of these two cases to decipher the poor prognosis dependent on the immunosuppressive barrier formed by FAP+ fibroblasts and SPP1+ macrophages in the SMARCA2-deficient while SMARCA4-preserved poorly differentiated lung adenocarcinoma (LUAD)." (PMID 40453096, 2025). "In lung adenocarcinoma, SPP1 has been linked with chemoresistance and unfavorable prognosis." (PMID 38430429, 2024). "Metformin exerted antitumor activities in part by regulating the AFAP1-AS1/miR-3163/secreted phosphoprotein 1 (SPP1) axis in lung adenocarcinoma, and miR-316 overexpression caused suppression of PI3K/AKT/mTOR signaling, which could be re-activated by SPP1 overexpression." (PMID 37686205, 2023). "Overall, VEGFA-, TIMP1, and SPP1-mediated regulatory networks may not only be the main cause of macrophage changes, but also these three signals may be markers of malignant changes in lung adenocarcinoma." (PMID 37189418, 2023). "Mechanistically, TNFAIP6 interacted with CD44 in lung adenocarcinoma cells, leading to increased extracellular availability of secreted phosphoprotein 1 (SPP1) within the TIME and the subsequent promotion of NETosis." (PMID 41899624, 2026). "We delineate the infiltration levels, intrinsic lineage trajectories, functional evolution, and crosstalk between eCAFs and SPP1+ macrophages in the lung adenocarcinoma microenvironment, as well as their prognostic value." (PMID 40657391, 2025). "In turn, NK cells in LUSC themselves also expressed higher Spp1 than did NK cells in lung adenocarcinoma." (PMID 40865052, 2025).
lung adenocarcinoma (continued). "SPP1 can upregulate PD-L1 to mediate M2 polarization of macrophages and promote immune escape in lung adenocarcinoma." (PMID 39616302, 2024). "For example, in lung adenocarcinoma, SPP1 expression on TAMs has been found to correlate with poor prognosis and chemoresistance." (PMID 39409192, 2024). "SPP1 + macrophages have been observed in lung adenocarcinoma lymph node metastasis and colon cancer liver metastasis." (PMID 38281962, 2024). "In lung adenocarcinoma, the upregulation of PD-L1 by SPP1 has been shown to mediate macrophage polarization, facilitate immune escape, and act as an immune checkpoint that induces host tumor immune tolerance by suppressing T cell activation." (PMID 39409192, 2024). "First because GJB2, expressed by tumor cells and cancer-associated fibroblasts (CAFs), contributes to ECM remodeling and activates the SPP1/PI3K/AKT signaling pathway in lung adenocarcinoma." (PMID 39737401, 2024). "Important regulatory molecules (VEGFA, TIMP1, SPP1, etc.)of macrophages in lung adenocarcinoma were identified by the gene regulatory network method." (PMID 37189418, 2023). "It was found that SPP1 was highly expressed in lung adenocarcinoma compared with normal lung tissue." (PMID 36688087, 2023). "SPP1 is not only a prognostic marker for lung adenocarcinoma, but also a marker for monocyte-derived macrophages in lung adenocarcinoma." (PMID 37190178, 2023). "The methylation level of SPP1 in lung adenocarcinoma is significantly decreased which is determined by the UALCAN online tool." (PMID 36688087, 2023). "Further investigation revealed which we were pleasantly surprised to find that both SPP1 and PIK3R1 were associated with lung adenocarcinoma prognoses and immunotherapy." (PMID 36688087, 2023). "To investigate the relationship between SPP1 and lung adenocarcinoma, we performed immunohistochemistry by using the HPA online tool." (PMID 36688087, 2023). "The difference expression of SPP1 in lung adenocarcinoma and normal tissues was analyzed by the HPA online tool." (PMID 36688087, 2023). "In vitro experiments in a mouse lung adenocarcinoma model have suggested that SPP1 mediates M2 polarization and the expression of IL-10, Arg1, and PD-L1, ultimately inhibiting CD4 T cells." (PMID 37251409, 2023). "At the same time, studies have found that SPP1 can regulate the expression of PD-L1 to mediate the immune escape of lung adenocarcinoma cells." (PMID 36688087, 2023). "We recently revealed that SPP1 expression on TAMs correlates with poor prognosis and chemoresistance in lung adenocarcinoma." (PMID 37190178, 2023). "In this review, we discussed the significance of TAM-derived SPP1 in the progression of lung adenocarcinoma." (PMID 37190178, 2023). "We recently revealed that SPP1 expression on TAMs is correlated with poor prognosis and chemoresistance in lung adenocarcinoma." (PMID 37190178, 2023). "In conclusion, SPP1 production on TAMs predicted a poor prognosis in lung adenocarcinoma patients, and TAM-derived SPP1′s involvement in the chemo-resistance of cancer cells was suggested." (PMID 36139536, 2022). "Intriguingly, SPP1 overexpression was reported to be associated with HCC progression and immune escape in lung adenocarcinoma." (PMID 35402515, 2022). "Both cell lines, A549 and HCC827, showed largely homogeneous staining for SPP1 in 2D and 3D cultures, comparable to that of lung adenocarcinoma specimens." (PMID 35565305, 2022). "In lung adenocarcinoma, single-cell sequencing identified a macrophage population overexpressing SPP1 and VEGFA." (PMID 36569953, 2022). "SPP1, also called osteopontin, is an arginine-glycine-aspartate-containing phosphoprotein that is overexpressed in many cancers, including lung adenocarcinoma and HCC, and serves as a prognostic biomarker." (PMID 36110938, 2022). "In this study, the SPP1 level on TAMs was found to be a predictor of a poor prognosis in lung adenocarcinoma." (PMID 36139536, 2022).
lung adenocarcinoma (continued). "We demonstrated that high SPP1 expression on TAMs predicted a poor prognosis in lung adenocarcinoma patients." (PMID 36139536, 2022). "TAMs also secreted SPP1 which have been found mediating macrophage polarization and facilitates immune escape in lung adenocarcinoma." (PMID 36685571, 2022). "Zhang found that SPP1 promotes immune escape of lung adenocarcinoma by mediating macrophage polarization." (PMID 35126478, 2022). "Previously, we found that lung adenocarcinoma cells induced M2 polarization of macrophages through SPP1, and activation of T cells were observed after SPP1 silencing." (PMID 34178613, 2021). "In agreement, Kaplan–Meier survival analysis showed that lower expression of SPP1 predicted significantly better outcomes in patients with lung adenocarcinomas (p = 0.015)." (PMID 34857857, 2021). "Our single-cell analysis indicated that expression of SPP1 and S100A6 were associated with global hypomethylation of lung adenocarcinoma cells." (PMID 34857857, 2021). "More reports had illustrated the relationship between the expression level of SPP1 and lung adenocarcinoma." (PMID 33968738, 2021). "In the pathological grade, the expression level of SPP1 was higher in lung adenocarcinoma samples whit moderately differentiated." (PMID 32595698, 2020). "Elevated levels of SPP1 expression were also found to correlate with highly aggressive lung adenocarcinoma." (PMID 33138195, 2020). "RNA data from the database TCGA showed that mRNA expression of ITGAV and ITGB3 correlated positively with SPP1 expression in lung adenocarcinoma and squamous patients." (PMID 33287873, 2020). "SPP1 has been reported to mediate macrophage polarization and induce immune escape in lung adenocarcinoma." (PMID 32158466, 2020). "In lung adenocarcinoma, SPP1 was found to up-regulate PD-L1 and subsequently facilitated the escape of immunity." (PMID 32849813, 2020). "A biomarker set of two genes, the MAP4 and SPP1, provides 99.36% accuracy for differentiating between lung adenocarcinomas and normal lung." (PMID 23369236, 2013). "Levels of SPP1 were also found to correlate with highly aggressive lung adenocarcinoma." (PMID 38167532, 2024). "SPP1 protein could also serve as a biomarker for identifying and predicting prognosis in lung adenocarcinoma and other cancers." (PMID 39766023, 2024). "Finally, we found that the immune checkpoint genes CD274(PD-L1) and PDCD1LG2(PD-1) were also related to SPP1 in lung adenocarcinoma." (PMID 36688087, 2023). "Surprisingly, SPP1 was highly expressed in lung adenocarcinoma compared to the normal lung tissue." (PMID 36688087, 2023). "Thus, targeting SPP1-related signaling pathways such as the SPP1/CD44 axis is a promising approach for the treatment of lung adenocarcinoma." (PMID 37190178, 2023). "Finally, we found that the immune checkpoint-related genes CD274(PD-L1) and PDCD1LG2(PD-1) was related to SPP1 in lung adenocarcinoma." (PMID 36688087, 2023). "We investigated the effects of the macrophage-derived SPP1 on lung adenocarcinoma cells." (PMID 36139536, 2022). "However, the role and biological function of SPP1 in lung adenocarcinoma (LUAD) was still ambiguous." (PMID 36266702, 2022). "The result of our finding that SPP1 may be a potential biomarker for lung adenocarcinoma was consistent with several studies." (PMID 33968738, 2021). "Co-expression of OCT4 and SPP1 may correlate with cancer aggressiveness, and the OCT4A/SPP1C axis may help identify early-stage high-risk patients with lung adenocarcinoma." (PMID 32503462, 2020). "Targeting VEGFA, TIMP1, and SPP1 may be a potential therapeutic strategy for lung adenocarcinoma." (PMID 37189418, 2023). "Thus, SPP1 derived from TAMs may be a target for anti-cancer therapy in lung adenocarcinoma patients." (PMID 36139536, 2022). "SPP1 could also mediate macrophage polarization and immune escape in lung adenocarcinoma." (PMID 33626243, 2021).
lung adenocarcinoma (continued). "Further evidence of the tumour‐promoting role of SPP1+ TAMs comes from a murine lung adenocarcinoma model, where a population of TREM2+ macrophages, also expressing the SPP1+ gene signature (TREM2, GPNMB, SPP1, CTSB, RNASE1, GPR183), was identified." (PMID 40395129, 2025). "According to TCGA database, SPP1 were significantly upregulated in many tumors, including UCEC, breast invasive carcinoma (BRCA), lung adenocarcinoma (LUAD) and colon adenocarcinoma (COAD)." (PMID 38956502, 2024). "Increased SPP1 expression and decreased E-cadherin expression were observed in the EMT area of lung adenocarcinoma, and an in vitro study revealed that SPP1-induced EMT was suppressed by inhibitors for PI3K/Akt and MAPK signals." (PMID 37190178, 2023). "Apart from two microRNA, miR-21-5p and miR-146a-5p are related to the prognosis of lung adenocarcinoma which are consistent to PIK3R1 and SPP1." (PMID 36688087, 2023). "Surprisingly, the survival analysis revealed that three genes (PIK3R1, SPP1, and PECAM1) have a clear correlation with OS in lung adenocarcinoma patients." (PMID 36688087, 2023). "Three genes (PIK3R1, SPP1, and PECAM1) have a clear correlation with OS in lung adenocarcinoma patients." (PMID 36688087, 2023). "We found three genes (PIK3R1, SPP1, and PECAM1) that have a clear correlation with OS in the lung adenocarcinoma patient." (PMID 36688087, 2023). "Silencing SPP1 was found to reduce EGFR resistance to tyrosine kinase inhibitors and reduce its invasiveness in lung adenocarcinoma." (PMID 36138770, 2022). "The strongest correlation was found between SPP1 gene expression and CD204 gene expression in lung adenocarcinoma tissues (Rho = 0.46, p < 0.001)." (PMID 36139536, 2022). "Hsa-mir-145 formed the third regulatory module for lung adenocarcinoma c with lncRNA C1orf220, which ranked second in potential lncRNAs, and mRNAs (COL1A2, COL3A1, SPP1, TIMP1 and CDH1)." (PMID 36138770, 2022). "We demonstrated that SPP1 and PIK3R1 were possible biomarkers of lung adenocarcinoma." (PMID 36688087, 2023). "We reveal two potential biomarkers for lung adenocarcinoma, including PIK3R1 and SPP1." (PMID 36688087, 2023). "We also investigated whether there was a correlation between SPP1 gene expression and various macrophage markers, such as CD204, Iba-1, CD68, CD163, and CD163L1, in lung adenocarcinoma tissues." (PMID 36139536, 2022). "SPP1 promotes proliferation, migration, invasion, and chemoresistance to cisplatin in NSCLC cells, and is important in mediating macrophage polarization and facilitating immune evasion in lung adenocarcinoma through the upregulation of PDL1." (PMID 34503105, 2021). "The expression of SPP1 in lung adenocarcinoma tissues and cells was significantly higher than that in normal tissues and cells and demonstrated positive correlation with TNM stage, lymph node metastasis, and invasion depth and negative correlation with survival." (PMID 37656377, 2023). "Thus, in this study, we tried to accurately evaluate the SPP1 expression status on cancer cells and TAMs separately in patients with NSCLC by double-IHC, and demonstrated that only SPP1 expression on TAMs predicted a poor prognosis in lung adenocarcinoma patients." (PMID 36139536, 2022). "Thus, in this study, we tried to accurately evaluate SPP1’s expression status on cancer cells and TAMs separately in patients with NSCLC by double-IHC and demonstrated that only SPP1 expression on TAMs predicted a poor prognosis in lung adenocarcinoma patients." (PMID 36139536, 2022).